CD68 (CD68 molecule)
Diseases named in the same sentence as CD68 in open-access papers (continued):
Sharing a sentence is not in itself a finding about the gene and the disease.
lung carcinoma (continued). "For example, the CD8, CD20, CD68, and CD4-positive exclusion group had the lowest degree of ITGAL-expressing cell infiltration in lung cancer tissues, whereas the inflamed group had the highest degree of ITGAL-expressing cell infiltration in lung cancer tissues." (PMID 38646528, 2024). "In parallel, TLR4 and CD68 were abundantly expressed and co-localized in cancerous areas but not adjacent tissues in samples from lung cancer patients." (PMID 36542153, 2022). "We observed increased BALF cell numbers and pulmonary CD68-positive macrophage infiltration in urethane-administered and HFD-fed mice compared to those in ND-fed mice, consistent with the increased lung cancer burden in urethane-administered and HFD-fed mice." (PMID 33708630, 2021). "In the CD68+ CD163+ M2 macrophage population, FRβ expression in lung cancer tissues was ~84–96%." (PMID 32296026, 2020). "Though the total count of CD68+ TAMs was not a prognostic factor, CD68+ TAM density in the lung cancer islet and stroma were both associated with patient survival." (PMID 27144518, 2016). "The number of cell with positive CD68 staining in adjacent lung cancer tissue was 97.49±2.54, which was higher than that in lung cancer tissues (11.78±1.37) and non-tumorous lung tissues (52.14±1.85), and the differences were significant (n = 67, P<0.05)." (PMID 23227270, 2012). "However, accumulating evidence suggested that S100A7 was negatively correlated with immune infiltration and immunomodulators in the lung cancer, for instance, expression of S100A7 could inhibit PD-L1, leading to down-regulating CD68+ macrophage infiltration." (PMID 38499391, 2024). "In the analysis, the histological lung cancer specimens from non-surviving patients displayed a distinct proinflammatory profile characterized by significantly higher levels of CD68 (macrophages) and IL-1β scores than the samples isolated from surviving patients." (PMID 35884397, 2022). "However, specific phenotypes in tumor islets and stroma were not identified in this study, and the role of CD68+ TAM amounts in lung cancer metastasis was not clarified." (PMID 33194645, 2020). "The neoplastic cells were positive for CD68 and CD163 and negative for epithelial antibodies; therefore, lung cancer was excluded." (PMID 36915094, 2023). "Our investigation showed that the cell density of CD68+ macrophages was significantly higher and that CD8+ T lymphocytes showed a clear tendency to be more significant in lung cancer patients with COPD than in those without COPD." (PMID 37388220, 2023). "In this study, the scRNA-seq analysis of patients with lung cancer showed MAFB expression in monocytes of tumor and advanced tumor tissue, while no other markers (CD204, CD68, CD206) were expressed." (PMID 36077342, 2022).
myocarditis (52 papers, 2011 to 2025). Myocarditis is a condition that is characterized by inflammation of the heart muscle (myocardium). "Collectively, our findings highlight the possible utility of supplemental CD68 IHC staining when performing EMB to aid in the diagnosis of ICI-associated myocarditis." (PMID 36915213, 2023). "This study requires additional validation of CD68 IHC staining in EMBs from patients with suspected ICI-associated myocarditis." (PMID 36915213, 2023). "Myocardial infiltration of CD68+ macrophages has previously been described in ICI-associated myocarditis with rapid and late onset." (PMID 36915213, 2023). "Previous studies have demonstrated that > 30 CD68+ macrophages/HPF are associated with high grade ICI-associated myocarditis." (PMID 36915213, 2023). "Inclusion of CD68 IHC could have potentially changed the certainty of the diagnosis of ICI-associated myocarditis to definite in 6/17 cases." (PMID 36915213, 2023). "However, we anticipate that CD68 IHC staining will improve the sensitivity of diagnosing ICI-associated myocarditis in the appropriate clinical context." (PMID 36915213, 2023). "Histologically, ICI-associated myocarditis is associated with infiltration of CD4+ and CD8+ T cells and CD68+ macrophages into the myocardium and conduction system." (PMID 40547024, 2025). "Histopathology confirmed focal necrosis, adipose infiltration, microvasculopathy with vascular smooth muscle cell (VSMC) proliferation, and CD68+ macrophage-mediated cardiomyocyte damage, consistent with myocarditis." (PMID 41303485, 2025). "In another pathological study, an increased ratio of CD68+ macrophages to CD3+ T cells was seen in higher grade forms of ICI myocarditis." (PMID 39023770, 2025). "Previous studies showed high amounts of CD68+ macrophages in cardiac tissue of patients who died or developed myocarditis after SARS-CoV-2 infection or vaccination." (PMID 39994453, 2025). "When compared to mock-infected mice, VA1-infected mice had a significant increase in CD68 +macrophages, consistent with definitions of myocarditis." (PMID 40304490, 2025). "From a histological perspective, myocarditis associated with ICIs is distinguished by the infiltration of CD4+/CD8+ T cells, CD68+ macrophages, and a decrease in other immune cell populations within the myocardium." (PMID 38482205, 2024). "In Case 4, the histopathological type was lymphocytic myocarditis (LM), showing 1 CD3-positive lymphocytes/mm2 and 7 CD68-positive histiocytes/mm2 were identified and classified as borderline myocarditis." (PMID 38275465, 2024). "Our results indicate that SSTR2 is expressed on the protein level on CD68-positive macrophages and multinucleated giant cells in different forms of myocarditis, such as LM, GCM, and CS." (PMID 39518342, 2024). "Altogether, these results emphasize the diagnostic utility of illustrating these cells using markers such as CD163 or CD68 in the evaluation of myocarditis." (PMID 39202593, 2024). "Supplemental IHC staining and quantification of CD68+ macrophages identified an additional 7 patients with pathological features of myocardial inflammation (> 50 CD68+ cells/HPF)." (PMID 36915213, 2023). "Based on positive CD68 IHC staining, we show potential clinical reclassification of patients from Possible or Probable to Definite myocarditis." (PMID 36915213, 2023). "While CD4+ and CD8+ cell infiltration prevails in typical inflammatory myocarditis, CD68+ cell infiltration is prevalent in SARS-CoV-2-induced myocarditis." (PMID 37112659, 2023). "Nine patients remained classified as Probable myocarditis and 6 remained classified as Possible myocarditis before and after CD68 staining." (PMID 36915213, 2023). "Champion and Stone (2020) have also demonstrated that more CD68+ macrophages were found in high-grade myocarditis cases (>50 CD3+ cells/high power field)." (PMID 35517794, 2022).
myocarditis (continued). "The distinction of leukocytes (CD45+), T lymphocytes (CD3+) and their subtypes (CD4+ or CD8+) and macrophages (CD68+) led to higher detection rates in the diagnosis of myocarditis, improving the sensitivity and specificity of the EMB." (PMID 35621854, 2022). "In another study, the miR-155 expression correlated with the number of CD68-positive cells (macrophages) during myocarditis." (PMID 36291684, 2022). "The lymphomononuclear infiltrates CD68- and CD45Ro+ were found, surrounded by focal necrosis of adjacent myocytes; these were indicative of myocarditis." (PMID 34573988, 2021). "Histology revealed mild infiltration with CD3-positive lymphocytes and CD68-positive macrophages, suggestive of mild myocarditis." (PMID 33871688, 2021). "The infiltrating CD68+ macrophages in ICI-induced myocarditis were noted in a patient with fatal myocarditis after a combination of CTLA-4 and PD-1 blockade." (PMID 31022941, 2019). "Histological analyses of patients and monkey models with ICI-associated myocarditis have revealed that the infiltration of predominant CD4+/CD8+ T lymphocytes and a few macrophages (CD68+ cells) are the main cause of ICI-associated myocarditis." (PMID 31849640, 2019). "Due to lack of technology in Sri Lanka, the current autopsy study did not proceed to detect dengue viral RNA or antigen in tissues or staining for T-cells (CD3) or macrophages (CD68) to strengthen the histopathological diagnosis of myocarditis." (PMID 21798066, 2011). "The biopsy indicated progression to chronic active myocarditis (CD68+)." (PMID 41303485, 2025). "Furthermore, the same authors report that in healing myocarditis, the lymphocytic infiltrate is reduced and mainly localized within the fibrous mesenchymal reparative tissue with a more evident share of CD68+ macrophages." (PMID 38611673, 2024). "Some preliminary reports suggest that the level of PD-L1 expression by CD68+ macrophages may correlate with the severity of myocarditis." (PMID 36672615, 2023). "However, there is no consensus for which IHC stains should be performed in cases of suspected ICI-associated myocarditis and several studies have reported a wide array of IHC staining including CD4, CD8, CD3, CD68, CD20, PD-1, and PD-L1." (PMID 36915213, 2023). "Two of the 8 patients originally classified as Possible myocarditis could be reclassified as Definite, given pathologic support of the diagnosis through evidence of cardiac inflammation with CD68 staining." (PMID 36915213, 2023). "When supplemental IHC staining in EMBs was performed, 7 additional patients could meet criteria for pathologic cardiac inflammation given positive CD68-IHC staining (> 50 CD68+ cells/HPF) and may be reclassified as having a Definitive diagnosis of ICI-associated myocarditis." (PMID 36915213, 2023). "Thus, our study highlights the possibility of transcriptomic alteration in mitochondrial metabolism-related genes as a biomarker of the vaccination-induced myocarditis, which is diagnosed with the findings that show the infiltration of CD68+ cells in cardiac tissues." (PMID 36225942, 2022). "IHC staining was performed using LCA, CD3, and CD68 to highlight leukocytes, T-lymphocytes, and macrophages, respectively, on cases 3, 5, and 7, in which H&E-stained tissue sections demonstrated histologic evidence that could be interpreted as myocarditis." (PMID 32552178, 2021). "A case report documented an instance of myocarditis with evidence of interstitial infiltration of the myocardium by CD3+-T lymphocytes and CD68+-macrophages." (PMID 39770819, 2024). "In Cases 1–6, the histopathologic type of myocarditis was lymphohistiocytic myocarditis, showing 2–10 CD3-positive infiltrating lymphocytes/mm2 and 0–10 CD68-positive infiltrating histiocytes/mm2." (PMID 38275465, 2024). "Lymphocytic infiltration within the myocardium, mainly positive for CD3 or the macrophage marker CD68, is the common pathological presentation of ICI-related myocarditis." (PMID 36032051, 2022).
myocarditis (continued). "All four patients with active myocarditis exhibited very mild infiltration of CD4+, CD8+, and CD20+ lymphocytes, and single or small clusters of CD68+ macrophages, and this pattern was also evident in all 22 patients without active myocarditis." (PMID 36312241, 2022). "Twenty studies included biopsy-verified myocarditis with findings of immune infiltration of the myocardium with CD4-positive T-lymphocytes, CD8-positive T-lymphocytes and CD68-positive macrophages." (PMID 34365980, 2021). "ICI-related myocarditis has been attributed to an immune infiltration, comprising of T-cells that are positive for CD3+, CD4+, CD8+, and macrophages that are positive for CD68." (PMID 34055610, 2021). "As a matter of fact, CD68+ macrophages and CD3+ lymphocytes were more abundant in the myocarditis group than in the control group." (PMID 34573988, 2021). "An early case report described the infiltration of CD68+ macrophages and CD4+ and CD8+ T cells into the myocardium of patients with ICI myocarditis, whereas in another case report, a predominance of CD8+ T cells was seen in the myocardium, with a decrease of Foxp3+ Treg cells." (PMID 39023770, 2025). "The densities of CD68+ macrophages and CD3+ lymphocytes have been reported to be relatively high in myocarditis, from the results of EMB; additionally, myocardial macrophage and lymphocyte densities displayed a positive correlation with the symptom duration of myocarditis." (PMID 38469104, 2024). "In the remaining 15 EMBs that did not meet the Dallas criteria for myocarditis on H&E staining, supplemental IHC staining for CD68 demonstrated increased macrophage infiltration in 7 samples." (PMID 36915213, 2023). "Autoimmune forms of myocarditis excluded, immunohistochemical examinations uniformly confirm that the inflammatory infiltrate is composed of activated CD3 T lymphocytes and CD68 macrophages (the human heart contains distinct macrophage subsets)." (PMID 37112659, 2023). "While medical records for these patients did not suggest myocarditis or notable viral infection, in myocardial sections from each we identified inflammatory infiltrates by immunohistochemistry with an anti-CD68 (cluster of differentiation 68) antibody." (PMID 37767697, 2023). "However, the myocardial CD68+/CD3+ ratio was found to be similar in high-grade and low-grade ICI-induced myocarditis." (PMID 36672615, 2023). "By analysing human endomyocardial biopsies, they found that immunohistological signs of inflammation such as CD68-positive cells, but not the abundance of cardiotropic viruses, predicted the outcome of patients with myocarditis." (PMID 33721106, 2021). "The cardiac tissue of infected mice at the acute state of myocarditis (7 days p.i.)revealed significantly increased numbers of CD11b+, CD68+, and CD80+ cells, whereas no increased inflammation was detected 28 days after CVB3 infection." (PMID 28352641, 2017). "The use of markers such as Leukocyte Common Antigen (LCA), CD68, CD45R0, and Major Histocompatibility Complex (MHC) class II molecules, along with detection of the VP1 capsid protein of enteroviruses, offers a comprehensive approach to confirm myocarditis presence in SIDS cases." (PMID 40566082, 2025). "Another study on biopsy‐proven lymphocytic myocarditis following mRNA COVID‐19 vaccination reported myocytes necrosis, CD68‐positive macrophages, and numerous CD3‐positive T cells, further corroborating the hypothesis that post‐vaccine myocarditis occurs via an immunologic response." (PMID 35652390, 2022). "Moreover, CD127 expression was previously reported for mouse intestinal macrophages, human CD68+ synovial macrophages or human CD68+ and CD163+ macrophages in cardiac ventricular tissues sampled from patients with myocarditis, as well as in vitro monocyte-derived human macrophages." (PMID 33717097, 2021).
myocarditis (continued). "Since CX3CL1 is expressed by CD68 and CD11b monocytes/macrophages and cardiac fibroblasts, the upregulation in LV CX3CL1 expression in CVB3-infected mice can partly be explained by the increase in monocytes/macrophages and cardiac fibroblast presence in myocarditis mice." (PMID 28800592, 2017). "Moreover, a recent investigation in patients with biopsy-proven myocarditis did not observe significant associations between outcome and immunohistochemical staining targets including CD3-positive T-lymphocytes or CD68-positive macrophages." (PMID 29267340, 2017). "The gold standard for diagnosing myocarditis is myocardial biopsy, which may demonstrate an intense, patchy lymphocytic infiltrate within the myocardium, that may also involve the cardiac sinus and atrioventricular nodes, positive for the T-cell marker CD3 or the macrophage marker CD68." (PMID 31417814, 2019). "Additionally, greater numbers of CD68-positive macrophages and CD3-positive T cells were present in patients with functional recovery, which indicated that the viability of cardiac tissue may be, at least in part, determined by immunocompetent cells and myocardial inflammation." (PMID 35229229, 2022). "An increase in the number of CD68+ macrophages was more frequently observed in patients with shorter intervals between the most recent positive SARS-CoV-2 PCR test and the time of performing the EMB (r = -0.33 and r = -0.61 for patients with and without myocarditis, respectively)." (PMID 37443606, 2023).